CYP2J2 (cytochrome P450 family 2 subfamily J member 2)
Description:
A cytochrome P450 monooxygenase involved in the metabolism of polyunsaturated fatty acids (PUFA) in the cardiovascular system. Mechanistically, uses molecular oxygen inserting one oxygen atom into a substrate, and reducing the second into a water molecule, with two electrons provided by NADPH via cytochrome P450 reductase (NADPH--hemoprotein reductase). Catalyzes the epoxidation of double bonds of PUFA. Converts arachidonic acid to four regioisomeric epoxyeicosatrienoic acids (EpETrE), likely playing a major role in the epoxidation of endogenous cardiac arachidonic acid pools. In endothelial cells, participates in eicosanoids metabolism by converting hydroperoxide species into hydroxy epoxy metabolites. In combination with 15-lipoxygenase metabolizes arachidonic acid and converts hydroperoxyicosatetraenoates (HpETEs) into hydroxy epoxy eicosatrienoates (HEETs), which are precursors of vasodilatory trihydroxyicosatrienoic acids (THETAs). This hydroperoxide isomerase activity is NADPH- and O2-independent. Catalyzes the monooxygenation of a various xenobiotics, such as danazol, amiodarone, terfenadine, astemizole, thioridazine, tamoxifen, cyclosporin A and nabumetone. Catalyzes hydroxylation of the anthelmintics albendazole and fenbendazole. Catalyzes the sulfoxidation of fenbedazole.
Synonyms: CPJ2; CYPIIJ2
Tractability: Small molecule: a high-quality ligand is known; it belongs to a druggable protein family. Antibody: UniProt places it where antibodies can reach, with medium confidence. PROTAC: its protein half-life has been measured; a small molecule that binds it is known.
Target class: Enzyme
Safety:
Unwanted effects reported when the protein is acted on. In parentheses: how it was acted on, where the effect was seen, and who reports it.
nausea and/or vomiting (source: ClinPGx)
Gene: Protein-coding gene on chromosome 1 (59,893,308 to 59,926,822, reverse strand). Ensembl gene ENSG00000134716.
Subcellular location: Endoplasmic reticulum membrane; Microsome membrane
Pathways (Reactome):
Metabolism: Fatty acids; Synthesis of epoxy (EET) and dihydroxyeicosatrienoic acids (DHET); Xenobiotics
Gene Ontology:
Molecular function: arachidonate 11,12-epoxygenase activity; arachidonate 14,15-epoxygenase activity; arachidonate 5,6-epoxygenase activity; arachidonate epoxygenase activity; isomerase activity; linoleic acid epoxygenase activity; heme binding; monooxygenase activity; oxidoreductase activity, acting on paired donors, with incorporation or reduction of molecular oxygen, reduced flavin or flavoprotein as one donor, and incorporation of one atom of oxygen; arachidonate 8,9-epoxygenase activity; hydroperoxy icosatetraenoate isomerase activity; iron ion binding; oxidoreductase activity, acting on paired donors, with incorporation or reduction of molecular oxygen
Biological process: epoxygenase P450 pathway; icosanoid metabolic process; linoleic acid metabolic process; fatty acid metabolic process; regulation of heart contraction; xenobiotic metabolic process; arachidonate metabolic process
Cellular component: extracellular exosome; cytoplasm; endoplasmic reticulum membrane
Genetic constraint (gnomAD): Loss-of-function variants: 41 observed, 50.16 expected, observed/expected ratio (o/e) 0.82, 90% interval 0.64 to 1.06. The upper end of that interval is the gene's LOEUF score, 1.06, which puts it in group 4 of 6, group 1 being the genes least tolerant of losing a copy. Missense variants: 644 observed, 649.27 expected, observed/expected ratio (o/e) 0.99, 90% interval 0.93 to 1.06. Synonymous variants: 221 observed, 240 expected, observed/expected ratio (o/e) 0.92, 90% interval 0.82 to 1.03.
Homologues: Orthologues: chimpanzee CYP2J2 (99% identical), macaque CYP2J2 (95% identical), dog CYP2J2 (79% identical), pig CYP2J34 (78% identical), rat Cyp2j9 (74% identical), mouse Cyp2j9 (73% identical), mouse Cyp2j13 (72% identical), rabbit CYP2J2 (67% identical). Paralogues in human: CYP2D6 (42% identical), CYP2R1 (42% identical), CYP2U1 (40% identical), CYP2B6 (40% identical), CYP2C8 (40% identical), CYP2A13 (39% identical), CYP2C19 (39% identical), CYP2C9 (39% identical), CYP2E1 (39% identical), CYP2F1 (39% identical), CYP2A7 (39% identical), CYP2A6 (38% identical), and 3 more.
Diseases named in the same sentence as CYP2J2 in open-access papers:
CYP2J2 is named in the same sentence as 95 diseases in open-access papers, as found by Europe PMC text mining. Sharing a sentence is not in itself a finding about the gene and the disease. The quoted sentences say what the papers report.
Hypertension (18 papers, 2011 to 2024). The presence of chronic increased pressure in the systemic arterial system. "CYP2J2*7 was also associated with an elevated risk of ischemic stroke in Chinese Han individuals and increased the risk of atherosclerosis, hypertension, and coronary artery disease in many ethnic groups." (PMID 37288113, 2023). "CYP2J2 coding for cytochrome P-450 2J2 is reported to be implicated in hypertension and coronary artery disease (CAD)." (PMID 37288265, 2023). "CYP450-epoxygenase (CYP2J2) polymorphisms have been reported in different populations related to its role in cardiovascular function, including hypertension." (PMID 32116704, 2020). "Some studies revealed that single nucleotide polymorphisms (SNPs) in the CYP4A11 and CYP2J2 genes were associated with human hypertension." (PMID 32116704, 2020). "Another study on CYP2J2 gene delivery via a recombinant adeno-associated virus in mice suppressed adventitial remodeling and inflammation and hypertension induced by angiotensin-II." (PMID 29966295, 2018). "CYP2J2 is primarily expressed in the aorta and coronary artery and has been linked to hypertension risk." (PMID 22577559, 2012). "Moreover, previous study confirmed TT homozygote carriers of CYP2J2 gene rs1155002 is susceptibility to essential hypertension, especially in females, and had higher systolic blood pressure in the Chinese Han population." (PMID 37288113, 2023). "An association between CYP2J2*7 and an increased risk of hypertension was found in a Caucasian population in Tennessee, in a Chinese Han population, in a Russian population, and in Saudi Arabian population but not in middle-aged Swedes and South Indian populations." (PMID 29966295, 2018). "Although CYP2J2 polymorphisms, particularly the 50G-T promoter polymorphism have been associated with cardiovascular disease and hypertension in some populations a polymorphisms of the CYP2J2 pathway has yet to be associated with any other form of inflammatory disorder in man." (PMID 24058654, 2013). "Administration of angiotensin II and high salt diet downregulated CYP2J2 in renal vessels leading to hypertension." (PMID 35903143, 2022). "On the other hand, the CYP2J2 activity is regulated by high-salt diet and suppression of CYP2J2 can lead to high blood pressure." (PMID 28900766, 2018). "Among these families, the CYP2J2 activity has been demonstrated to be regulated by high-salt diet and its suppression could result in hypertension." (PMID 38355434, 2024). "In fact, it has been found that a single nucleotide polymorphism (SNP) in the CYP2J2 gene (the CYP2J2*7 genotype) was associated with hypertension in males, but not in females of a Caucasian population." (PMID 25426071, 2014). "Cardiac-specific CYP2J2 overexpression had beneficial effects on cardiovascular disease progression and recovery, such as improving the outcomes of ischemia and/or ischemia‒reperfusion injuries, decreasing arrhythmia of hypertension and delaying hypertension development." (PMID 37288113, 2023). "Therefore, high salt diets influence CYP2J2 activity, and the suppression of this gene could result in high blood pressure." (PMID 35903143, 2022). "Additionally, about ten different SNVs for the CYP2J2 gene are known, but their clinical role was mainly studied in the context of coronary heart disease (CAD) and arterial hypertension, since isoenzyme CYP2J2 encoded by this gene plays a role in the metabolism of arachidonic acid." (PMID 33922084, 2021). "Although more research is necessary to confirm the relevance of CYP to sodium-induced hypertension in humans, our results corroborate human research showing that CYP2J2 and CYP4A11 are related to hypertension." (PMID 31065462, 2019). "Numerous studies have demonstrated that elevation of EETs by overexpression of CYP2J2, inhibition of sEH, or treatment with EET analogs showed protective effects in various cardiovascular diseases, including hypertension, myocardial infarction, and heart failure." (PMID 33716791, 2021).
Hypertension (continued). "Although not conclusive, CYP2J2 genetic variation may reduce EET levels, which could potentially lead to hypertension." (PMID 29966295, 2018).
cardiac hypertrophy (14 papers, 2013 to 2026). "In a transgenic mouse model that overexpressed CYP2J2 in cardiomyocytes, cardioprotective EETs were generated that protected against arrhythmia susceptibility in cardiac hypertrophy." (PMID 33561224, 2021). "Another study demonstrated that overexpression of cardiac CYP2J2 in a transgenic mouse model lowers arrhythmia susceptibility in cardiac hypertrophy." (PMID 29966295, 2018). "Our study shows that cardiomyocyte-specific overexpression of the human epoxygenase CYP2J2 protects against arrhythmia susceptibility in two mouse models of cardiac hypertrophy." (PMID 24023684, 2013). "Conversely, transgenic over-expression of human CYP2J2 in murine cardiomyocytes enhances EpFA production which preserves cardiac function in ischemia-reperfusion injury, diabetic cardiomyopathy, and attenuates arrythmia susceptibility in cardiac hypertrophy." (PMID 35665247, 2022). "The same group also showed that cardiomyocyte-specific overexpression of CYP2J2 in mice reduced damage associated with cardiac hypertrophy and heart failure and prevented endoplasmic reticulum (ER)-stress and subsequent apoptosis that occurred in heart failure." (PMID 29966295, 2018). "Chronic ISO infusion caused moderate cardiac hypertrophy in both WT and CYP2J2-TG mice." (PMID 24023684, 2013). "Cardiac CYP2J2 overexpression significantly attenuates Angiotensin II (Ang II)-induced cardiac hypertrophy." (PMID 38921429, 2024). "In the context of TAC induced cardiac remodeling, the cardiomyocytes’ specific expression of CYP2J2 not only inhibited cardiac hypertrophy, but also significantly alleviated the electrical remodeling." (PMID 35744996, 2022). "Meanwhile, CYP2J2 and EETs enhanced Akt1 nuclear translocation through interaction with AMPKα2β2γ1 and subsequently attenuated cardiac hypertrophy." (PMID 35744996, 2022). "In the hypertrophic heart, the levels of EETs were observed, while restoring EET levels by overexpression of CYP2J2 prevented the initiation of cardiac hypertrophy through NF-κB-mediated mechanism." (PMID 33716791, 2021). "For example, overexpression of CYP2J2 is beneficial in the treatment of diabetes and in the reduction of cardiac hypertrophy." (PMID 34258261, 2021). "Westphal et al16 firstly reported that transgenic mice with cardiomyocyte‐specific overexpression of CYP2J2 enhanced cardiac EET biosynthesis, reducing ventricular tachyarrhythmia and AF susceptibility during maladaptive cardiac hypertrophy." (PMID 31749335, 2020). "This study also went on to demonstrate that cardiac CYP2J2 overexpressing mice were protected from the cardiovascular consequences of diabetes, in particular myocardial hypertrophy." (PMID 29966295, 2018). "Together, these results suggest that CYP2J2 overexpression protects against development of cardiac hypertrophy and cardiac remodeling and that CYP2J2‐mediated cardioprotection is accompanied by an increase in ANP expression." (PMID 27416746, 2016). "We have confirmed CYP2J2 overexpression increased the activity of AMPK in Ang II‐induced cardiac hypertrophy." (PMID 27416746, 2016). "Overall, our data indicate that CYP2J2 and its metabolites EETs inhibited cardiac hypertrophy through the activation of AMPKα2." (PMID 27416746, 2016). "Echocardiography results showed CYP2J2 overexpression plays little role against Ang II‐induced cardiac hypertrophy in AMPKα2−/− mice." (PMID 27416746, 2016). "In order to exclude the effect of blood pressure lowering by CYP2J2 in the development of cardiac hypertrophy, we used hydralazine (100 mg L−1) to reduce the blood pressure, the effect of which was consistent with CYP2J2 overexpression." (PMID 27416746, 2016). "The survival rate during the development of pressure overload-induced cardiac hypertrophy was significantly higher in CYP2J2-TG compared to WT mice." (PMID 24023684, 2013).
cardiac hypertrophy (continued). "In a TAC model, cardiac function could be restored by CYP2J2 overexpression and changes in expression of CYP450 enzymes and their associated metabolites contribute to the initiation of cardiac hypertrophy." (PMID 36531184, 2022). "In this study, we investigated whether the CYP2J2, or EETs, could suppress cardiac hypertrophy by activating AMPKα2." (PMID 27416746, 2016). "In our current study, CYP2J2 overexpression significantly prevented Ang II‐induced cardiac hypertrophy, and therefore, we speculated CYP2J2 may have important protective effects against aging‐induced cardiac hypertrophy and consequential heart failure." (PMID 27416746, 2016). "The forced expression of CYP2J2 prevented Ang II‐induced cardiac hypertrophy in mice." (PMID 27416746, 2016). "Although the functional roles of AMPK and Akt are well established, the significance of cross talk between them in the development of cardiac hypertrophy and antihypertrophy of CYP2J2 and EETs remains unclear." (PMID 27416746, 2016). "Furthermore, CYP2J2 overexpression ameliorated Ang II‐induced expression of the biomarkers of cardiac hypertrophy brain natriuretic peptide (BNP), β‐myosin heavy chain (β‐MHC), and skeletal muscle α‐actin (ACTA1)." (PMID 27416746, 2016). "We investigated whether CYP2J2 and its metabolites EETs protected against cardiac hypertrophy by activating AMPKα2 and Akt1." (PMID 27416746, 2016). "Interestingly, overexpression of CYP2J2 suppressed cardiac hypertrophy and increased levels of atrial natriuretic peptide (ANP) in the heart tissue and plasma of wild‐type mice but not AMPKα2−/− mice." (PMID 27416746, 2016). "We found that CYP2J2 overexpression mediated strong antiarrhythmic effects in both models, suggesting that EETs are involved in endogenous mechanisms preventing maladaptive electrical remodeling during cardiac hypertrophy." (PMID 24023684, 2013). "TAC-induced cardiac hypertrophy was associated with significant QRS prolongation in WT but not CYP2J2-TG mice." (PMID 24023684, 2013). "Moreover, CYP2J2-derived EETs also showed protective effects on cardiac hypertrophy." (PMID 33716791, 2021). "Thus, it was reasonable to postulate that AMPKα2 activation might mediate the protective effects of CYP2J2 overexpression or EETs against the development of cardiac hypertrophy." (PMID 27416746, 2016). "Our studies reveal a novel mechanism in which CYP2J2 and EETs enhanced Akt1 nuclear translocation through interaction with AMPKα2β2γ1 and protect against cardiac hypertrophy and suggest that overexpression of CYP2J2 might have clinical potential to suppress cardiac hypertrophy and heart failure." (PMID 27416746, 2016). "Thus, CYP2J2, EETs, and downstream signaling molecules may be novel therapeutic targets for protection against the development of cardiac hypertrophy and consequential heart failure." (PMID 27416746, 2016). "We used CYP2J2-transgenic mice to test the hypothesis that enhanced cardiac EET biosynthesis prevents arrhythmogenic substrate formation during the development of maladaptive cardiac hypertrophy." (PMID 24023684, 2013). "It is believed that inhibition of endoplasmic reticulum (ER) stress and oxidative stress was involved in the effects of overexpression of CYP2J2 and exogenous 11,12-EET, which finally ameliorated cardiac hypertrophy." (PMID 33716791, 2021). "Coincidentally, our laboratory also showed that overexpression of CYP2J2 and 11,12-EET attenuated cardiac hypertrophy elicited with Ang II, which was mediated through the activation of AMPK-α2." (PMID 33716791, 2021). "A few reports have demonstrated that increased CYP2J2 activity and EET production mitigates cardiac hypertrophy." (PMID 29966295, 2018). "Taken together, these results indicate that CYP2J2 or its metabolite 11,12‐EET induced the nuclear accumulation of p‐Akt1 via AMPKα2 to prevent development of cardiac hypertrophy." (PMID 27416746, 2016).
cardiac hypertrophy (continued). "Accumulating evidence suggests that both CYP2J2 and its EET metabolites may confer protection against the development of cardiac hypertrophy." (PMID 41602333, 2026). "Cytochrome P450 2J2 (CYP2J2) is an epoxygenase enzyme that mediates the formation of epoxyeicosatrienoic acids (EETs), and overexpression of this enzyme in mouse hearts suppresses cardiac hypertrophy and increases levels of atrial natriuretic peptide (ANP)." (PMID 32503253, 2020). "The CYP2J2 metabolites, 11,12‐EET, activated AMPKα2 to induce nuclear translocation of p‐Akt1 selectively, which increased the production of ANP and therefore inhibited the development of cardiac hypertrophy." (PMID 27416746, 2016). "Ang II‐induced increased heart size, area of the cardiomyocytes, fibrosis of cardiomyocytes, and biomarkers of cardiac hypertrophy were not attenuated after CYP2J2 overexpression in AMPKα2−/− mice." (PMID 27416746, 2016). "In our current study, overexpression of CYP2J2 attenuated cardiac hypertrophy in AMPKα2+/+ mice that underwent Ang II infusion, but not in AMPKα2−/− mice similarly treated." (PMID 27416746, 2016). "In contrast to these profound effects on electrical remodeling, CYP2J2 overexpression only moderately reduced TAC-induced cardiac hypertrophy and did not affect the hypertrophic response to β-adrenergic stimulation." (PMID 24023684, 2013). "In summary, elevation of endogenous EETs by overexpression of CYP2J2 and sEH inhibition, as well as EET analogs, showed protective effects against cardiac remodeling, which was mediated mainly by prohibiting inflammation, apoptosis, fibrosis, and cardiac hypertrophy and promoting angiogenesis." (PMID 33716791, 2021). "Thus, we speculate that CYP2J2 and EETs might regulate the expression of ANP through the activation of AMPKα2 to attenuate cardiac hypertrophy." (PMID 27416746, 2016). "Importantly, CYP2J2 and EET induced the formation of the AMPKα2β2γ1–pAkt1 complex, leading to the nuclear translocation of p‐Akt1, which, in turn, upregulated the expression of ANP, attenuating cardiac hypertrophy." (PMID 27416746, 2016).